NR1D1 (nuclear receptor subfamily 1 group D member 1)
Diseases named in the same sentence as NR1D1 in open-access papers (continued):
Sharing a sentence is not in itself a finding about the gene and the disease.
colitis (25 papers, 2018 to 2025). Inflammation of the colon. "Berberine alleviates colitis in vivo and in vitro, but this effect is abolished in BMDMs from NR1D1-deficient mice." (PMID 38072952, 2023). "NR1D1 knockout mice were more susceptible to experimental colitis, suggesting an essential role of NR1D1 in colitis development." (PMID 35893911, 2022). "On the contrary, we found that in colorectal stromal cells, colitis was associated with decreases in the mRNA levels of Arntl, Clock, Cry1, Cry2, Per2, Per3, Nr1d1, Npas2, and BBR restored the expression of these genes except Per2." (PMID 36528592, 2022). "Immunofluorescence of tight‐junction proteins ZO‐1 and occludin showed reduced expression in Nr1d1−/− colons during colitis, consistent with impaired barrier integrity." (PMID 41163542, 2025). "Functional experiments demonstrate that NR1D1 deficiency enhances epithelial apoptosis, upregulates CD47, impairs macrophage efferocytosis, and exacerbates colitis in IEC‐specific Nr1d1−/− mice." (PMID 41163542, 2025). "Proteomic profiling of IECs from Nr1d1−/− and WT mice with colitis revealed substantial differences in protein expression." (PMID 41163542, 2025). "Here, this study shows that NR1D1 expression is markedly reduced in human UC biopsies and murine colitis." (PMID 41163542, 2025). "To test the therapeutic potential of NR1D1 activation in colitis, we administered the synthetic agonist SR9011 to mice subjected to DSS‐induced inflammation." (PMID 41163542, 2025). "Together, these results demonstrate that HA@Alg‐ADAP‐SR9011 provides sustained, intestine‐targeted NR1D1 activation, attenuating inflammation and promoting mucosal homeostasis in experimental colitis." (PMID 41163542, 2025). "To assess the role of NR1D1 in intestinal inflammation, we generated IEC‐specific Nr1d1 knockout mice (Nr1d1−/−) and induced colitis with dextran sulfate sodium (DSS)." (PMID 41163542, 2025). "To assess epithelial apoptosis, we performed TUNEL staining on colonic tissues, which revealed significantly increased apoptotic cell numbers in Nr1d1−/‐ mice during colitis." (PMID 41163542, 2025). "After establishing the mouse models, we isolated the IECs and discovered that jet lag and colitis impacted the expression pattern of clock genes, resulting in reduced NR1D1 expression." (PMID 37762536, 2023). "Administering the NR1D1 agonist SR9009 ameliorated colitis symptoms, primarily by rectifying defective mitophagy." (PMID 37762536, 2023). "We engineered mouse models simulating both jet lag and colitis, enabling the observation of alterations in the expression dynamics of clock genes within IECs, specifically the notable downregulation of NR1D1." (PMID 37762536, 2023). "Our investigation provides evidence that the NR1D1 agonist SR9009 promotes survival during colitis, restricts excessive mitophagy, and ameliorates UC in murine models." (PMID 37762536, 2023). "Mechanistically, berberine attenuates the inflammatory response to colitis in BMDMs and colitis mice by activating the NR1D1/AMPK pathway and inhibiting the activator protein 1 (AP-1) and NF-κB pathways." (PMID 38072952, 2023). "Colitis was more severe in Nr1d1−/− mice than in WT mice, with significant damage to the colonic mucosa." (PMID 37762536, 2023). "Recent studies have shown that disrupting genetic components of the circadian clock mechanism including the genes Per1/2, Nr1d1, and Rorα result in increased colitis severity." (PMID 35223537, 2022). "NR1D1 regulates BNIP3-mediated mitophagy in ulcerative colitis to alleviate colitis symptoms." (PMID 38732079, 2024). "Pharmacological NR1D1 activation represses pro-inflammatory cytokine secretion and promotes IL-10 in primary rat microglia, in murine models of colitis, in the lungs of murine models of inhaled LPS, in the livers of murine models of fulminant hepatitis, and in murine and human macrophages." (PMID 36860863, 2023).
colitis (continued). "However, this increase in Nr1d1 in controls is subtle, consistent with previous reports that have shown Nr1d1 expression is suppressed during colitis." (PMID 35223537, 2022). "We also compared the expression of several key circadian genes including Arntl, Clock, Cry1, Cry2, Per1, Per2, Per3, Nr1d1, and Npas2 in colon samples collected at 03, 09, 15, and 21 of normal mice, colitis mice, normal mice receiving BBR, and colitis mice receiving BBR." (PMID 36528592, 2022). "Interestingly, an agonist of NR1D1 attenuates both dextran sodium sulfate (DSS)-induced colitis and D-galactosamine-induced fulminant hepatitis suggesting that NR1D1-mediated circadian control of Nlrp3 expression controls inflammation in vivo." (PMID 33138274, 2020). "Moreover, NR1D1, as a transcriptional repressor, could repress the NF-κB/Nlrp3 axis to prevent colitis." (PMID 35893911, 2022). "Pharmacological activation of NR1D1 using a bioadhesive hydrogel delivering SR9011 restores intestinal immune balance, reduces CD47 expression, and ameliorates colitis severity." (PMID 41163542, 2025). "Specifically, we show that SR9011‐activated NR1D1 reduces CD47 expression, enhances macrophage‐mediated clearance of apoptotic cells, and significantly improves disease outcomes in a murine colitis model." (PMID 41163542, 2025). "Restoring rhythmic NR1D1 activation using SR9011‐loaded bioadhesive hydrogel enhances efferocytosis, improves epithelial homeostasis, and ameliorates colitis severity." (PMID 41163542, 2025). "Targeted activation of NR1D1 through rhythm‐sensitive hydrogel‐based delivery of SR9011 restores mucosal immune balance and attenuates colitis." (PMID 41163542, 2025). "In Nr1d1 mutants treated with DSS, inflammation is exacerbated leading to increased DSS-induced colitis." (PMID 35223537, 2022). "In vivo evidence revealed that the absence of NR1D1 aggravated the severity of DSS-induced colitis, establishing NR1D1 as a pivotal nexus between circadian rhythms and UC manifestation." (PMID 37762536, 2023). "However, these genes are redundant in terms of clock function, hence the colitis phenotypes of the mutants are most likely attributable to Nr1d1 and Rorα function rather than a result of circadian rhythm loss which persists in the mouse strains used in these studies." (PMID 35223537, 2022).
breast carcinoma (21 papers, 2009 to 2025). "Aside from this, it was shown that NR1D1 improved the susceptibility of breast cancer cells to DNA damage-induced chemotherapy, hence increasing the likelihood of PCR in breast cancer patients." (PMID 35481240, 2022). "Although recent studies have implicated NR1D1 as a regulator of DNA repair and proliferation in breast cancers, its potential as a therapeutic target for breast cancer has not been assessed in terms of clinical outcomes." (PMID 31779659, 2019). "Several studies have reported that NR1D1 is closely associated with the pathophysiology of breast cancer." (PMID 31779659, 2019). "Over-expression of PBP and NR1D1 in ERBB2-positive breast cancer cells causes these cells to store fatty acids at 10 times the level of other breast cancer cells (Kourtidis A, Carkner RD, Eifert C, Brosnan MJ, Conklin DS; unpublished data)." (PMID 19298655, 2009). "The variations were located mainly in the first intron and in the 5′ untranslated region of NR1D1, which may cause differential expression of the gene, as shown in breast cancer patients." (PMID 31779659, 2019). "Additionally, NR1D1 is associated with chemosensitivity of breast cancer." (PMID 34330232, 2021). "It has been demonstrated that NR1D1, also known as REV-ERB-α, inhibits the growth of ovarian cancer and is related to the prognosis of breast cancer." (PMID 38480634, 2024). "NR1D1 inhibits the DNA repair of ROS-induced DNA damage in breast cancer cells and enhances the accumulation of DNA damage, thereby increasing the sensitivity of breast cancer cells to oxidative stress." (PMID 39559540, 2024). "In breast cancer, the antiproliferative effects of NR1D1 were achieved by targeting cyclin A2 and interfering with the cancer cell cycle." (PMID 38480634, 2024). "Consistently, activation of NR1D1 was also reported to reduce the level of cyclinA in breast cancer cells." (PMID 34330232, 2021). "In breast cancer patients with chemotherapy, NR1D1 is a prognostic marker predicting good prognosis." (PMID 34162762, 2021). "It is known that ERBB2 is closely associated with NR1D1, the gene that encodes REV-ERBα (a clock protein involved in the secondary clock TTFL), and high levels of NR1D1 have frequently been found in breast cancer patients." (PMID 34842634, 2021). "SR9011, a synthetic ligand of NR1D1, has been reported to inhibit the proliferation of various breast cancer cell lines and to induce cell cycle arrest by suppressing cyclin A." (PMID 31779659, 2019). "In breast cancer cells, NR1D1 is recruited to DNA damage sites and therein interacts with poly (ADP-ribose) polymerase 1 (PARP1) and subsequently inhibits the recruitment of the DNA damage response complex including SIRT6, pNBS1, and BRCA1." (PMID 31779659, 2019). "Although NR1D1 implicates as a regulator of DNA repair and proliferation in breast cancers, its potential as a therapeutic target for breast cancer has not been assessed in clinical outcomes." (PMID 31779659, 2019). "Subgroup analysis performed according to molecular subtype of breast cancer showed a significant influence of high NR1D1 expression on OS (P = 0.002) and DFS (P = 0.007) in patients with triple-negative breast cancer (TNBC) treated with chemotherapy." (PMID 31779659, 2019). "GSK4112, a synthetic ligand of NR1D1, increased the chemosensitivity of breast cancer cells to doxorubicin." (PMID 31779659, 2019). "Subgroup analyses according to molecular subtype of breast cancer in patients treated with chemotherapy showed significant influences of high NR1D1 expression on OS (P = 0.002) and DFS (P = 0.007) in TNBC patients who received chemotherapy." (PMID 31779659, 2019). "NR1D1 expression was analyzed by immunohistochemistry using an anti-NR1D1 antibody in 694 breast cancer samples." (PMID 31779659, 2019). "One hundred thirty-nine of these samples exhibited high NR1D1 expression, mostly in the nucleus of breast cancer cells." (PMID 31779659, 2019).
breast carcinoma (continued). "The gene sequence of PBP and NR1D1 are located in the ERBB2 amplicon, and in breast cancer, mutations in this gene locus are linked to high lipid synthesis and PBD, NR1D1 overexpression." (PMID 29966227, 2018). "NR1D1 circadian transcription factor has found to be co-amplified with the receptor ERBB2 in “HER2-positive breast cancer” and probably contribute to the aggressiveness of this malignancy." (PMID 28177907, 2017). "Basal tumors are characterized by lower NR1D1 contents than Luminal-A, Luminal-B or Her2 breast-cancers." (PMID 26894976, 2016). "The genetic linkage between NR1D1, PBP, and ERBB2 causes co-overexpression of these gene products such that ERBB2-positive breast cancer cells are preprogrammed to depend on fatty acid synthesis for energy production and survival." (PMID 19298655, 2009). "Although most of the literature on NR1D1 has been centered on its role as a transcriptional repressor in circadian rhythm, lipid metabolism, and inflammation, only one group has shown that NR1D1 regulates DNA repair at the post-translational level in breast cancer models." (PMID 34743206, 2022). "Although NR1D1 may provide therapeutic options for improving the outcome of chemotherapy in breast cancer patients, its potential as a therapeutic target for breast cancer has not been clearly assessed in clinical outcomes." (PMID 31779659, 2019). "NR1D1 is located in the ERBB2 amplicon region of chromosome 17q12–21 and is thought to be part of the ERBB2 signature, which is associated with poor clinical outcome in breast cancer." (PMID 31779659, 2019). "Therefore, in the present investigation, we performed a retrospective study to investigate NR1D1 expression in breast cancer patients and to evaluate its potential prognostic value." (PMID 31779659, 2019). "Thus, this study aims to analyze NR1D1 expression in breast cancer patients and to evaluate its potential prognostic value." (PMID 31779659, 2019). "Thus, NR1D1 may be a therapeutic target for breast cancer treatment, especially in patients treated with ROS-inducing chemotherapy drugs." (PMID 39559540, 2024). "Thus, the role of genetic variations in NR1D1 in the pathogenesis and progression of breast cancer as well as the chemotherapeutic responses may be an important issue." (PMID 31779659, 2019). "While no studies on NR1D2 in mammary-tumors are available, NR1D1 may exert onco-suppressive effects, as silencing causes reduced growth/apoptosis of HER2+/BT-474 and ER+/MCF-7 cells." (PMID 26894976, 2016). "The expression of six rhythm genes, CRY2, NFIL3, PER1, EGR3, NR1D1 and TIMELESS, was significantly changed in breast cancer compared with normal breast tissues." (PMID 35180863, 2022). "The pro-adipogenic transcriptional regulators, PPARγ binding protein (PBP) and RevERBα/NR1D1 cooperatively contribute to increased expression of pro-lipogenic enzymes and a unique, Warburg-like metabolism in HER2/neu-positive breast cancer cells." (PMID 27464732, 2016). "PPARγ activity is necessary for the viability specifically of ERBB2-positive breast cancer cells, in a similar manner to PBP and NR1D1 (Kourtidis A, unpublished data; Carkner RD, Eifert C, Brosnan MJ, Conklin DS)." (PMID 19298655, 2009). "PPARγ inhibition in ERBB2-positive breast cancer cells resulted in cell death and apoptosis, similar to the effects of PBP and NR1D1 inhibition (Kourtidis A, Carkner RD, Eifert C, Brosnan MJ, Conklin DS; unpublished data)." (PMID 19298655, 2009). "The tight genetic linkage between PBP, NR1D1, and ERBB2 on the 17q12-21 amplicon commonly found in breast cancers suggests that ERBB2-positive breast cancer cells are genetically preprogrammed to depend on fatty acid synthesis for energy production." (PMID 19298655, 2009).
breast carcinoma (continued). "Another recent study showed that a nuclear receptor, NR1D1, enhances the antitumor CD8 + T cell response to breast cancer by promoting DNA damage-induced accumulation of cytosolic DNA fragments, which leads to activation of cGAS-STING signaling and downstream type I IFN signaling." (PMID 41299712, 2025). "NR1D1 expression did not correlate significantly with OS (P = 0.266) or DFS (P = 0.387) in the breast cancer patients when all the samples were included in the analysis." (PMID 31779659, 2019). "Two datasets included in this meta-analysis studied NR1D1 SNPs in ER positive and negative breast cancer patients, but they fail to find any statistically significant association with cancer risk." (PMID 28177907, 2017). "Overall survival (OS) and disease-free survival (DFS) did not correlate significantly with NR1D1 expression in breast cancer patients regardless of whether they had received chemotherapy." (PMID 31779659, 2019). "We recently showed that ERBB2-positive breast cancer cells produce significantly high amounts of fats, because of overexpression of the peroxisome proliferator-activated receptor (PPAR)γ-binding protein and the nuclear receptor NR1D1 (nuclear receptor subfamily 1, group D, member 1; Rev-erbα)." (PMID 19298655, 2009). "A synthetic NR1D1 agonist, SR9011, suppresses the proliferation of breast cancer cells regardless of the molecular subtype of breast cancer." (PMID 31779659, 2019).
depression (18 papers, 2009 to 2025). "In the targeted examination of circadian genes, significant associations (padj < 0.05) of depression with NR1D1 (Z = 4.23, p = 1.16 × 10–5) and PER1 (Z = 2.94, p = 0.002) were observed." (PMID 36131119, 2022). "Findings from the targeted examination of clock genes revealed several significant associations with depression (NR1D1 and PER1) and BIP-I (ARNTL, CRY2, RORB) underlining the close relationship with mood disorders." (PMID 36131119, 2022). "Supporting these observations, the genes Nr1d1 and Bhlhe41, which have been associated with the control of circadian rhythm function and depression, were downregulated in the PFC of transgenic mice." (PMID 33795014, 2021). "Several circadian genes were upregulated, including CLOCK, ARNTL, CRY1, DBP, and NR1D1; with associations found between CLOCK and lower state anxiety at baseline, and between CRY2 and higher self-esteem and lower depression at baseline (p < 0.05)." (PMID 41383341, 2025). "A recent human postmortem study indicates that clock genes (including NR1D1) are rhythmically expressed in the brain regions involved in mood regulation, but these rhythms are attenuated in subjects with major depressive disorder." (PMID 32190129, 2020). "Of them, NR1D1 genetic variants have been demonstrated to associate with bipolar disorders and depressive disorders, CRY2 (cryptochrome 2) with depressive disorders and bipolar disorders, and CRY1 (cryptochrome 1) with depressive disorders." (PMID 25610405, 2014). "Clock gene Arntl, Nr1d1, Per2 and Cry2 expression in the hippocampus was increased in subjects with substance use disorder, while Arntl and Nr1d1 expression was decreased in subjects with major depression." (PMID 37441675, 2023). "Arntl and Nr1d1 expression in comparison was decreased in subjects with major depression." (PMID 36161151, 2022). "After LBRD standard decoction administration, four differentially expressed miRNAs, rno-miR-144-3p, rno-miR-495, rno-miR-34c-5p, and rno-miR-24-3p, and six differentially expressed mRNAs, Calml4, Ntrk2, VGAT, Gad1, Nr1d1, and Bdnf overlapped in the in vivo/vitro depression model." (PMID 34674715, 2021). "It is noteworthy that the genes, such as Hbb-b1, Nr1d1 and so on, are upregulated in the CUMS-induced depression mice, though their roles in major depression are unclear." (PMID 27427907, 2016). "The expressions of Hbb-b1 and Nr1d1 are raised, as well as the expressions of Gad1, Mbp and Slc6a11 are decreased in CUMS-induced depression mice, compared to the control mice (p<0.01)." (PMID 27427907, 2016). "PPARGC1A possibly binds to RORE sites both on NR1D1 and on ARNTL, and PPARGC1B may act similarly, perhaps providing a partial explanation for effects on both mania and depression, seeming opposites which are both aspects of bipolar disorder." (PMID 19166596, 2009). "By stimulatory binding at D-box promoter sites, TEF may promote transcription of NR1D1, NR1D2, and the PER genes, actions which might be supposed to stimulate mania or counter depression." (PMID 19166596, 2009). "A NR1D1 SNP that was previously found to be associated with bipolar disorder, rs2314339, was significantly associated with QIDS-SR by our meta-analysis, but we have not discovered any previous replication in unipolar depression studies." (PMID 23521777, 2013).